HCN4 (hyperpolarization activated cyclic nucleotide gated potassium channel 4)
Diseases named in the same sentence as HCN4 in open-access papers (continued):
Sharing a sentence is not in itself a finding about the gene and the disease.
colorectal cancer (1 paper, 2020). A primary or metastatic malignant neoplasm that affects the colon or rectum. "Here we demonstrated that CGI hypermethylation of FIGN, HTRA3, BDNF, HCN4 and STAC2 in colorectal cancer is associated with patient progression to metastasis, identifying them as putative future biomarkers for CRC progression." (PMID 32971738, 2020). "Statistical association between poor survival and hypermethylation of CGI was established in FIGN (p = 0.030), HTRA3 (p = 0.009), BDNF (p = 0.002), HCN4 (p = 0.018) and STAC2 (p = 0.007) and may be used as potential markers for metastasis progression in colorectal cancer." (PMID 32971738, 2020). "In addition, the hypermethylation of FIGN, HTRA3, BDNF, HCN4 and STAC2 could be utilised in primary tumour as biomarkers of colorectal cancer prognosis." (PMID 32971738, 2020).
diabetic cardiomyopathy (1 paper, 2021). Diabetic cardiomyopathy is a disorder of the heart muscle in people with diabetes. "We focused on miR-1 and miR-133a as their dysregulation contributes to diabetic cardiomyopathy and moreover, also influences HCN2 and HCN4 expressions." (PMID 33653265, 2021).
dilated cardiomyopathy (1 paper, 2020). Cardiomyopathy which is characterized by dilation and contractile dysfunction of the left and right ventricles. "For example, decreased MYL2 and MYH6 gene expression coincided with increased RYR2, HCN4, CORIN, NPPA, ERBB2, and MYH7 gene expression in hypertrophic and/or dilated cardiomyopathy." (PMID 32804947, 2020).
fibrosis (1 paper, 2019). the formation of excess fibrous connective tissue in an organ or tissue in a reparative or reactive process. "However, HCN4 overexpression did not induce cardiac fibrosis, and we observed no myocyte disarray or cellular infiltrations." (PMID 31337768, 2019).
genetic generalized epilepsy (1 paper, 2022). A generalized epilepsy that is understood to have a genetic etiology. "HCN1 p.L157V and HCN4 p.R550C were associated with genetic generalized epilepsy." (PMID 35663267, 2022).
hyperglycaemia (1 paper, 2021). "We hypothesized that myocardial alterations in HCN2 and HCN4 channels occur under hyperglycaemia." (PMID 33653265, 2021).
hyperthyroidism (1 paper, 2023). Overactivity of the thyroid gland resulting in overproduction of thyroid hormone and increased metabolic rate. "At the molecular level, such resistance occurs despite expected upregulation of Hcn2 and Hcn4, indicating that these classical T3 target genes alone are not sufficient to mediate the tachycardia of hyperthyroidism." (PMID 37286550, 2023).
hypertrophic cardiomyopathy (1 paper, 2021). A condition in which the myocardium is hypertrophied without an obvious cause. "It was reported for hypertrophic cardiomyopathy, with particular emphasis on the abnormal ventricular expression of HCN4, the predominant isoform of human and mouse auricles." (PMID 34835334, 2021). "Furthermore, HCN4 was found overexpressed in cats with hypertrophic cardiomyopathy, and both mRNA and protein levels of HCN4 were significantly augmented in failing human ventricles." (PMID 34835334, 2021).
infantile epilepsy (1 paper, 2018). "In order to broaden the analysis of potential pathogenic mechanisms and novel pharmacological targets, it would be important to include HCN4 in the screening of the genetic factors contributing to infantile epilepsies." (PMID 30127718, 2018). "Since HCN4 appears to be highly expressed in deep brain structures only early during development, our data provide a potential explanation for a link between dysfunctional HCN4 and infantile epilepsy." (PMID 30127718, 2018).
injury (1 paper, 2020). Damage inflicted on the body as the direct or indirect result of an external force, with or without disruption of structural continuity. "For example, a downregulation in HCN1 subunit expression (which confer faster kinetics on HCN channel complexes) in iPVINs, coupled with an increased expression of the more slowly conducting HCN4 subunits, could contribute to the reduced excitability seen in these cells after nerve injury." (PMID 33029722, 2020).
left ventricular hypertrophy (1 paper, 2016). Enlargement of the LEFT VENTRICLE of the heart. "Upregulation of HCN4 has been observed in the ventricles of rats with hypertrophy resulting from pressure overload and left ventricular hypertrophy is a common finding in obese individuals." (PMID 27747100, 2016).
myocardial disease (1 paper, 2015). "A dnNRSF-expressing transgenic mouse model with gradually progressive myocardial disease was demonstrated to overexpress HCN2 and HCN4 in the ventricle." (PMID 26005035, 2015).
myocarditis (1 paper, 2021). Myocarditis is a condition that is characterized by inflammation of the heart muscle (myocardium). "Following this line of thought, this work explored the possible role of HCN4 in acute chagasic myocarditis." (PMID 34835334, 2021).
Noncompaction cardiomyopathy (1 paper, 2019). A type of cardiomyopathy characterized anatomically by deep trabeculations in the ventricular wall, which define recesses communicating with the main ventricular chamber. "We and others reported that HCN4 loss-of-function mutations are associated with noncompaction cardiomyopathy, pointing to an involvement of HCN4 in ventricular wall maturation at embryonic stages." (PMID 31337768, 2019).
Obesity (1 paper, 2016). Accumulation of substantial excess body fat. "We observed significant upregulation in HCN4 at the mRNA and protein levels in the left ventricle in obesity, a key pacemaker channel." (PMID 27747100, 2016). "We have shown that a diet rich in saturated fats leading to obesity results in significant upregulation of Cav1.2, HCN4, Kir2.1, NCX1, SERCA2a, and RYR2 mRNA and significant downregulation of ERG mRNA in the left ventricle." (PMID 27747100, 2016).
situs inversus (1 paper, 2017). A congenital condition in which there is complete right-to-left reversal of the position of the major thoracic and abdominal organs (that is, they are arranged in a mirror image of the normal positioning). "Similar to HCN4, disrupting cytoskeletal dynamics causes a major incidence of situs inversus." (PMID 28818840, 2017). "Situs inversus is the most frequent phenotype observed upon pharmacologically blocking HCN4 during early embryogenesis." (PMID 28818840, 2017). "Interestingly, blocking the HCN4 channel early leads to a major incidence of situs inversus and a small incidence of the bilateral gut (isomerism); it should be noted that gut isomerism is extremely rare in the extensive Xenopus literature on left-right-randomizing treatments." (PMID 28818840, 2017).
ventilator-associated pneumonia (1 paper, 2025). Serious INFLAMMATION of the LUNG in patients who required the use of PULMONARY VENTILATOR. "In ventilator-associated pneumonia (VAP), distinct gene expression profiles have been identified, showing downregulation of genes like PIK3R3, ATP2A1, PI3, ADAM8, and HCN4." (PMID 39941194, 2025).
cardiac diseases (5 papers, 2010 to 2024). "Previous studies have shown that many cardiac diseases can cause remodeling of major ion channels including HCN1 and HCN4, A1R, and L-type calcium channels." (PMID 31980605, 2020). "The pathological mechanisms of hereditary cardiac diseases due to CAV3 mutations that have been described so far reported a direct influence of the CAV3 mutants on the activity of membrane ion channels localized within caveolae (Nav 1.5, Cav1.2, Kir2.1, Kv4.2, HCN4)." (PMID 38256054, 2024).
cancer (3 papers, 2020 to 2025). A tumor composed of atypical neoplastic, often pleomorphic cells that invade other tissues. "HCN4 and STAC2 have otherwise not been reported in cancer research so far, especially not regarding their methylation status." (PMID 32971738, 2020).
tumor (2 papers, 2020 to 2022). "Concentrations of Gamitrinib that trigger tumor cell killing (IC50 ~1-4 μM) do not affect cytochrome P450 isoforms CYP1A2, CYP2A6, CYP2B6, CYP2C8 or ion channel conductance (Nav1.5, Kv4.3/KChIP2, Cav1.2, Kv1.5, KCNQ1/mink, HCN4, Kir2)." (PMID 35129069, 2022).
cardiovascular diseases (1 paper, 2021). "In conclusion, SFI promotes HCN4 activity in BMSCs, which could explain its treatment effect when administered to patients with cardiovascular diseases." (PMID 34457032, 2021).
HCN4 also shares sentences with these, for which no sentence is quoted: cardiac arrhythmias (6 papers); atrial tachycardia (2); Long QT Syndrome (2); absence seizures (1); angina (1); atrial standstill (1); breast tumour (1); cardiac conduction disease (1); congenital heart disease (1); convulsion (1); diabetes (1); epileptic syndrome (1); Hypertension (1); idiopathic generalized epilepsy (1); idiopathic ventricular tachycardia (1); infarction (1); infection (1); ischemic cardiomyopathy (1); Left ventricular noncompaction cardiomyopathy (1); lipodystrophy (1); long QT syndrome types 1 (1); mitral valve prolapse (1); short QT syndrome (1); Stroke (1); tuberculosis (1); valvular heart disease (1); ventricular fibrillation (1); Ventricular hypertrophy (1).